ZSCAN21 (zinc finger and SCAN domain containing 21)
Description:
Strong transcriptional activator (By similarity). Plays an important role in spermatogenesis; essential for the progression of meiotic prophase I in spermatocytes (By similarity).
Synonyms: ZNF38; DKFZp434L134; NY-REN-21; Zipro1
Tractability: PROTAC: UniProt records ubiquitination sites on it; ubiquitination databases record sites on it; its protein half-life has been measured.
Gene: Protein-coding gene on chromosome 7 (100,049,772 to 100,065,044, forward strand). Ensembl gene ENSG00000166529.
Subcellular location: Nucleus
Subcellular location (Human Protein Atlas): Endoplasmic reticulum
Gene Ontology:
Molecular function: DNA-binding transcription activator activity, RNA polymerase II-specific; protein binding; RNA polymerase II cis-regulatory region sequence-specific DNA binding; DNA-binding transcription factor activity, RNA polymerase II-specific; DNA binding
Biological process: positive regulation of transcription by RNA polymerase II; regulation of DNA-templated transcription; male meiosis I; regulation of transcription by RNA polymerase II; spermatogenesis; positive regulation of DNA-templated transcription
Cellular component: nucleus
Genetic constraint (gnomAD): Loss-of-function variants: 36 observed, 44.66 expected, observed/expected ratio (o/e) 0.81, 90% interval 0.62 to 1.06. The upper end of that interval is the gene's LOEUF score, 1.06, which puts it in group 4 of 6, group 1 being the genes least tolerant of losing a copy. Missense variants: 593 observed, 609.36 expected, observed/expected ratio (o/e) 0.97, 90% interval 0.91 to 1.04. Synonymous variants: 219 observed, 226.13 expected, observed/expected ratio (o/e) 0.97, 90% interval 0.87 to 1.08.
Homologues: Orthologues: chimpanzee ZSCAN21 (99% identical), macaque ZSCAN21 (98% identical), guinea pig ZSCAN21 (86% identical), rabbit ZSCAN21 (83% identical), rat Zscan21 (83% identical), mouse Zscan21 (82% identical). Paralogues in human: ZKSCAN8 (47% identical), ZKSCAN3 (46% identical), ZSCAN30 (46% identical), ZKSCAN4 (46% identical), ZSCAN12 (45% identical), ZNF397 (45% identical), ZKSCAN1 (43% identical), ZNF165 (41% identical), ZNF394 (40% identical), ZNF449 (40% identical), ZSCAN31 (40% identical), ZNF263 (39% identical), and 18 more.
Diseases named in the same sentence as ZSCAN21 in open-access papers:
ZSCAN21 is named in the same sentence as 2 diseases in open-access papers, as found by Europe PMC text mining. Sharing a sentence is not in itself a finding about the gene and the disease. The quoted sentences say what the papers report.
Parkinson disease (3 papers, 2021 to 2025). A progressive degenerative disorder of the central nervous system characterized by loss of dopamine producing neurons in the substantia nigra and the presence of Lewy bodies in the substantia nigra and locus coeruleus. "The transcription factor ZSCAN21 has been shown to act on SNCA, but whether ZSCAN21 is actually involved in the induction of SNCA transcription in Parkinson’s disease is unknown." (PMID 40379611, 2025). "ZSCAN21 (also known as Zipro1/RU49/ZNF38) is a transcription factor regulating the SNCA gene which encodes α-synuclein, an abundant presynaptic protein whose deregulation is involved in Parkinson’s disease." (PMID 34069831, 2021).
ZSCAN21 also shares sentences with these, for which no sentence is quoted: asthma (1 paper).